CFAP107 (cilia and flagella associated protein 107)
Description:
Microtubule inner protein (MIP) part of the dynein-decorated doublet microtubules (DMTs) in cilia axoneme, which is required for motile cilia beating.
Synonyms: C1orf158; MGC35194
Tractability: Small molecule: a structure with a bound ligand is known.
Gene: Protein-coding gene on chromosome 1 (12,746,200 to 12,763,699, forward strand). Ensembl gene ENSG00000157330.
Subcellular location: Cytoplasm, cytoskeleton, cilium axoneme; Cytoplasm, cytoskeleton, flagellum axoneme
Subcellular location (Human Protein Atlas): Cytosol
Gene Ontology:
Biological process: flagellated sperm motility
Cellular component: axonemal microtubule; axonemal A tubule inner sheath; sperm flagellum; axoneme
Genetic constraint (gnomAD): Loss-of-function variants: 14 observed, 14.19 expected, observed/expected ratio (o/e) 0.99, 90% interval 0.65 to 1.53. The upper end of that interval is the gene's LOEUF score, 1.53, which puts it in group 6 of 6, group 1 being the genes least tolerant of losing a copy. Missense variants: 222 observed, 231.95 expected, observed/expected ratio (o/e) 0.96, 90% interval 0.86 to 1.07. Synonymous variants: 85 observed, 91.38 expected, observed/expected ratio (o/e) 0.93, 90% interval 0.78 to 1.11.
Homologues: Orthologues: chimpanzee CFAP107 (99% identical), macaque CFAP107 (94% identical), rabbit CFAP107 (82% identical), pig CFAP107 (78% identical), guinea pig CFAP107 (77% identical), dog CFAP107 (75% identical), mouse Cfap107 (75% identical), rat Cfap107 (75% identical), zebrafish si:ch211-226m7.4 (39% identical).
Diseases named in the same sentence as CFAP107 in open-access papers:
CFAP107 is named in the same sentence as 1 disease in open-access papers, as found by Europe PMC text mining. Sharing a sentence is not in itself a finding about the gene and the disease.
CFAP107 shares sentences with these, for which no sentence is quoted: sarcoidosis (1 paper).